ITFG1 (integrin alpha FG-GAP repeat containing 1)
Description:
Modulator of T-cell function. Has a protective effect in graft versus host disease model (By similarity).
Synonyms: LNKN-1; TIP; CDA08; 2310047C21Rik; LINKIN
Tractability: Antibody: UniProt places it where antibodies can reach, with high confidence; UniProt predicts a signal peptide or a membrane-spanning region; its Gene Ontology location is reachable by antibodies, with medium confidence. PROTAC: ubiquitination databases record sites on it; its protein half-life has been measured.
Gene: Protein-coding gene on chromosome 16 (47,154,387 to 47,464,149, reverse strand). Ensembl gene ENSG00000129636.
Subcellular location: Secreted; Membrane
Subcellular location (Human Protein Atlas): Golgi apparatus; Vesicles
Gene Ontology:
Cellular component: extracellular exosome; plasma membrane; extracellular region; membrane
Genetic constraint (gnomAD): Loss-of-function variants: 4 observed, 14.78 expected, observed/expected ratio (o/e) 0.27, 90% interval 0.13 to 0.62. The upper end of that interval is the gene's LOEUF score, 0.62, which puts it in group 2 of 6, group 1 being the genes least tolerant of losing a copy. Missense variants: 220 observed, 224.88 expected, observed/expected ratio (o/e) 0.98, 90% interval 0.88 to 1.09. Synonymous variants: 103 observed, 96.03 expected, observed/expected ratio (o/e) 1.07, 90% interval 0.91 to 1.26.
Homologues: Orthologues: chimpanzee ITFG1 (99% identical), macaque ITFG1 (99% identical), dog ITFG1 (95% identical), pig ITFG1 (93% identical), rabbit ITFG1 (92% identical), mouse Itfg1 (89% identical), rat Itfg1 (88% identical), guinea pig ITFG1 (81% identical), tropical clawed frog itfg1 (68% identical), zebrafish itfg1 (66% identical), Drosophila melanogaster CG7739 (36% identical), Caenorhabditis elegans lnkn-1 (28% identical).
Diseases named in the same sentence as ITFG1 in open-access papers:
ITFG1 is named in the same sentence as 5 diseases in open-access papers, as found by Europe PMC text mining. Sharing a sentence is not in itself a finding about the gene and the disease.
ITFG1 shares sentences with these, for which no sentence is quoted: epilepsy (1 paper); infection (1); malaria (1); Neurodevelopmental delay (1); rheumatoid arthritis (1).